ENSG00000200288
Synonyms: LOC124900562
Gene: Small nucleolar RNA gene on chromosome 3 (177,624,282 to 177,624,409, reverse strand). Ensembl gene ENSG00000200288.
Gene Ontology:
Biological process: RNA processing
Cellular component: nucleolus
Homologues: Paralogues in human: SNORA18 (94% identical).